NPSR1-AS1 (NPSR1 antisense RNA 1)
Synonyms: AAA1; IMAGE:4827585
Gene: Long non-coding RNA gene on chromosome 7 (34,287,269 to 34,871,582, reverse strand). Ensembl gene ENSG00000197085.
Diseases named in the same sentence as NPSR1-AS1 in open-access papers:
NPSR1-AS1 is named in the same sentence as 16 diseases in open-access papers, as found by Europe PMC text mining. Sharing a sentence is not in itself a finding about the gene and the disease.
NPSR1-AS1 shares sentences with these, for which no sentence is quoted: atherosclerosis (2 papers); Hepatic steatosis (2); abdominal aortic aneurysm (1); cardiovascular disease (1); Cirrhosis (1); coronary artery calcification (1); COVID-19 (1); Erythema (1); infection (1); liver (1); liver fibrosis (1); metabolic syndrome (1); non-alcoholic steatohepatitis (1); Obesity (1); steatosis (1); Stroke (1).